CD151 (CD151 molecule (Raph blood group))
Diseases named in the same sentence as CD151 in open-access papers (continued):
Sharing a sentence is not in itself a finding about the gene and the disease.
lymphoma (2 papers, 2023 to 2025). A malignant (clonal) proliferation of B- lymphocytes or T- lymphocytes which involves the lymph nodes, bone marrow and/or extranodal sites. "We identified a new association of CD151 with ITGB2 in lymphoma cells that is important for cell spreading." (PMID 40464949, 2025). "B lymphoma cell lines and human lymphoma biopsy samples expressed higher levels of CD151 compared to normal B cells, but CD151‐deficient lymphomas were identified as well." (PMID 40464949, 2025). "Our study identified higher CD151 expression in lymphomas compared to normal B cells, thus we analyzed CD151 expression levels in relation to clinical outcome in a well-defined cohort of R-CHOP-treated DLBCL patients." (PMID 40464949, 2025). "Together, these data show that CD151 expression is higher on lymphomas compared to normal B cells, where its expression increases during B cell differentiation." (PMID 40464949, 2025). "Next, integrin-free and total CD151 expression in lymphoma cells was assessed, showing a homogeneous, mostly integrin-free CD151 expression on the surface of different lymphoma cell lines, which is in line with primary B cells." (PMID 40464949, 2025). "Most lymphoma cell lines showed detectable CD151 cell surface protein expression, which varied in levels." (PMID 40464949, 2025). "We verified CD151 expression in primary human lymphomas and analyzed publicly available data from the German MMML consortium (Molecular Mechanisms in Malignant Lymphoma) for CD151 mRNA expression." (PMID 40464949, 2025). "Immunoprecipitation-mass spectrometry analysis of CD151 protein complexes identified integrin beta 2 (ITGB2) as new interaction partner in lymphoma cells." (PMID 40464949, 2025). "Several knockouts illustrate their biological functions such as infertility (CD9/CD81), lymphoma development (CD37), immunological deficiency (CD81), or renal insufficiency (CD151)." (PMID 37835445, 2023). "In this study we report increased expression of CD151 in lymphomas compared to healthy B cells." (PMID 40464949, 2025). "Within the group of lymphoma cell lines, a range of CD151 mRNA expression was observed that was not linked to a specific type of B cell lymphoma." (PMID 40464949, 2025). "Interestingly, B cells and lymphomas did not express ITGA3‐bound CD151 compared to T cells that expressed two different populations of integrin‐bound and integrin‐free CD151." (PMID 40464949, 2025).
pancreatic adenocarcinoma (2 papers, 2015 to 2022). "We recently uncovered by a CD151 knockdown (CD151kd) in a rat pancreatic adenocarcinoma that CD151 promotes adhesion, which is overcome by CD151-associated MMPs degrading the extracellular matrix." (PMID 25544774, 2015). "Tspan8 and CD151 are metastasis-promoting tetraspanins and a knockdown (kd) of Tspan8 or CD151 and most pronounced of both tetraspanins affects the metastatic potential of the rat pancreatic adenocarcinoma line ASML." (PMID 25544774, 2015). "This feature becomes of particular interest for tetraspanins that are engaged in metastasis formation, which is well known for CD151 and Tspan8, the latter also being a CIC marker in pancreatic adenocarcinoma." (PMID 25544774, 2015).
prostate tumor (2 papers, 2014). "Secondly, recent work in our laboratory has shown that deletion of Cd151 reduces spontaneous metastasis of prostate tumors in the TRAMP model." (PMID 25012362, 2014).
pulmonary fibrosis (2 papers, 2020). Chronic progressive interstitial lung disorder characterized by the replacement of the lung tissue by connective tissue, leading to progressive dyspnea, respiratory failure, or right heart failure. "TGF-β signaling is crucial in lung fibrosis and we had demonstrated that Cd151-deletion augmented TGF-β signaling in the development of lung fibrosis." (PMID 33424923, 2020). "The authors concluded that CD151 functions to protect against pulmonary fibrosis by maintaining epithelial integrity." (PMID 32117989, 2020). "Interestingly, CD151-null mice spontaneously developed pulmonary fibrosis features observed at 30 weeks and exhibited accelerated bleomycin-induced lung injury in the pulmonary fibrosis model, suggesting a protective role of CD151 in IPF." (PMID 32117989, 2020). "Our results, therefore, suggested that Cd151-deletion directly induced increased collagen deposition and ECM-remodeling that may eventually lead to progressive lung fibrosis." (PMID 33424923, 2020). "We had previously demonstrated that Cd151 is necessary for the integrity of the alveolar epithelial cells (AECs); Cd151 deletion had resulted in the activation of phosphorylated Smad2 and EMT-like changes that may potentially contribute to the development of pulmonary fibrosis in the mouse lung." (PMID 33424923, 2020).
rectal cancer (2 papers, 2022 to 2024). A primary or metastatic malignant neoplasm that affects the rectum. "LncRNA DLGAP1-AS2 enhanced the radiotherapy resistance of rectal cancer cells by interacting with E2F1 to increase CD151 expression through activating the AKT/mTOR/cyclinD1 signaling pathway." (PMID 39119602, 2024).
serous ovarian cancer (2 papers, 2014 to 2022). "In this regard, the tumor-suppressive function of CD151-integrin complexes described in the current study may be partially associated with unique oncogenic activations in human serous ovarian cancer revealed by recent genome-wide analyses." (PMID 25356755, 2014).
skin squamous cell carcinoma (2 papers, 2020 to 2024). A carcinoma arising from the squamous cells of the epidermis. "For example, TSPAN24 (CD151) was found to influence the association of integrin α6β4 with protein kinase C; activate STAT3 (a transcription factor constitutively active in many human malignancies); and support de novo tumor initiation, promotion and progression of skin squamous cell carcinoma." (PMID 32138170, 2020).
Stroke (2 papers, 2020 to 2021). Sudden impairment of blood flow to a part of the brain due to occlusion or rupture of an artery to the brain. "Neurological outcomes were examined at 24 and 72 h after reperfusion to investigate the effect of the CD151 downregulation on experimental stroke outcomes in rats." (PMID 34022890, 2021). "For example, a preclinical trial studying CD151, a member of the transmembrane four superfamilies that plays a key role in maintaining vascular stability, showed that its upregulation in the early phases of stroke is able to preserve BBB integrity, turning it into a possible therapeutic target." (PMID 33362697, 2020).
acute myeloid leukaemia (1 paper, 2014). "The tetraspanin CD151/TSPAN 24/PETA3 was originally identified in platelet and endothelial cells by using a monoclonal antibody against human acute myeloid leukaemia cells." (PMID 24553111, 2014).
B cell lymphomas (1 paper, 2025). "We investigated CD151 expression on normal human B cells and B cell lymphomas using highly sensitive flow cytometry and immunohistochemistry." (PMID 40464949, 2025). "Therefore, we studied the association of CD151 with ITGA3 in normal healthy B cells and B cell lymphomas." (PMID 40464949, 2025). "We identified integrin beta 2 (ITGB2, CD18) as a novel binding partner of CD151 in B cell lymphoma." (PMID 40464949, 2025). "Contrary to T cells, B cells, and B cell lymphomas expressed CD151 with a free ITGA3 binding domain, and targeting integrin-free CD151 in DLBCL may represent a new target for immunotherapy." (PMID 40464949, 2025). "Here we report CD151 expression and its molecular interaction with ITGB2 in B cell lymphomas." (PMID 40464949, 2025). "CD151 expression has been well-established to correlate with poor prognosis for patients with different solid cancer types due to enhanced metastasis among other mechanisms, but this has not yet been established for B-cell non-Hodgkin lymphoma." (PMID 40464949, 2025).
bone metastasis (1 paper, 2022). Transfer of a neoplasm from its primary site to bones. "Upregulated GDF11 and CD151 expressions were positively correlated with bone metastasis, whilst the inverse correlation was shown with the other seven." (PMID 35685372, 2022).
Burkitt lymphoma (1 paper, 2025). A rare form of malignant mature B-cell non-Hodgkin lymphoma. "CD151 expression was highest in DLBCL and FL, and lowest in Burkitt lymphoma (BL) and primary B cells." (PMID 40464949, 2025).
carcinosarcoma (1 paper, 2011). A malignant tumor composed of a mixture of carcinomatous and sarcomatous elements. "Expression of CD151 was significantly higher in uterine papillary serous and clear cell carcinoma than in grade 3 endometrioid carcinoma, sarcoma or carcinosarcoma (P<0.001)." (PMID 21505452, 2011).
Cerebral ischemia (1 paper, 2021). Restriction of arterial blood supply to the brain associated with insufficient oxygenation to support the metabolic requirements of the tissue. "Here, we examined the expression levels of VCAM-1, ICAM-1, E-selectin, and CD9 in vivo and in vitro to confirm the effects of CD151 on endothelial cell adhesion molecules within the TEMs in cerebral ischemia." (PMID 34022890, 2021). "Then, immunohistochemistry and myeloperoxidase activity assessment were performed to explore the effects of CD151 expression on neutrophil and monocyte recruitment after rat cerebral ischemia." (PMID 34022890, 2021). "This work aimed to investigate the therapeutic value of CD151 downregulation and its function in leukocyte infiltration after cerebral ischemia." (PMID 34022890, 2021). "The effect of CD151 in the hyperacute and long-term phase after cerebral ischemia will be examined." (PMID 34022890, 2021). "In this study, we first demonstrated that the downregulation of CD151 decreased the VCAM-1 on endothelial cells, thereby restraining neutrophil and monocyte infiltration and improving neurological outcomes after cerebral ischemia." (PMID 34022890, 2021). "Therefore, the MAPK and NF-κB pathways were involved in the consistent expression of CD151 and VCAM-1 in endothelial cells after cerebral ischemia." (PMID 34022890, 2021).
Clear Cell Renal Cell Carcinoma (1 paper, 2018). "Only few studies have reported that CD151 might characterize metastatic potential in Clear Cell Renal Cell Carcinoma (ccRCC) and could be a prognostic marker for progression of ccRCC." (PMID 29568359, 2018).
dengue (1 paper, 2025). "In this study, we aimed to examine the expression levels of three molecules, CD151, CD154, and CD148 on platelets in dengue patients." (PMID 39710119, 2025). "Expression levels of CD151 remained unchanged in dengue patients irrespective of the dengue disease category when compared to healthy subjects." (PMID 39710119, 2025).
depression (1 paper, 2016). "To confirm this, we found that miR-124 inhibitor can partly rescue CD151 level from shR-PIK3C2A mediated depression." (PMID 27270320, 2016).
diffuse large B-cell lymphoma (1 paper, 2025). "In addition, we detected a significant increase in CD151 expression in diffuse large B cell lymphoma (DLBCL) and follicular lymphoma (FL) compared to healthy B cells." (PMID 40464949, 2025).
disc degeneration (1 paper, 2023). "Cluster 5 exhibited the most distinction and is marked by expression of alarmins and the surface antigens Cd81 and Cd151; thus, these surface markers could be used to specifically isolate and define the roles of this macrophage subset to disc degeneration." (PMID 38274272, 2023).
E. coli infection (1 paper, 2020). "Six genes (CLDN20, PARD6B, CD151, CDH11, CLDN2 and F11R) related to the GO biological process “Cell junction organization” were upregulated by E. coli infection, whereas these genes were not induced by EPS." (PMID 32234079, 2020).
embryonic carcinoma (1 paper, 2023). "In addition to an important role in PRRSV replication, CD151 interacts with integrin to promote outgrowth in human embryonic carcinoma cell line NT2N." (PMID 37099541, 2023).
emphysema (1 paper, 2020). "By analyzing transcriptomic data from transgenic mice deficient in Cd151 (an in vivo model of IPF) or Cd9 (an in vivo model of emphysema), we obtained deeper insights into their functions in lung pathology." (PMID 33424923, 2020). "Our analysis has provided novel insights into the contrasting roles of Cd151 and Cd9 in the pathogenesis of IPF and emphysema, respectively." (PMID 33424923, 2020).
endothelial dysfunction (1 paper, 2018). In vascular diseases, endothelial dysfunction is a systemic pathological state of the endothelium (the inner lining of blood vessels) and can be broadly defined as an imbalance between vasodilating and vasoconstricting substances produced by (or acting on) the endothelium. "Similarly, knockdown of CD151 induced endothelial dysfunction, as demonstrated by reduced migration, impaired tube formation, and damaged NO release." (PMID 29581851, 2018).
experimental autoimmune encephalomyelitis (1 paper, 2019). An autoimmune demyelinating disease of the central nervous system that is produced experimentally in animals by the injection of homogenized brain or spinal cord in Freund's adjuvant. "Encephalitogenic T cells from Myelin Oligodendrocyte Glycoprotein (MOG)-Induced Experimental Autoimmune Encephalomyelitis (EAE) mice showed significantly lower levels of TSPAN32 and increased levels of CD9, CD53, CD82 and CD151." (PMID 31487788, 2019).
Flavivirus Infections (1 paper, 2025). Infections with viruses of the genus FLAVIVIRUS, family FLAVIVIRIDAE. "Hence, we investigated the role of mosquito CD151 (a human ortholog of CD151) in ZIKV/DENV2 infection to understand the molecular mechanism of CD151-mediated flavivirus infections." (PMID 40806523, 2025). "The role of the specific tetraspanin CD151 in flavivirus infection is not yet addressed in arthropods." (PMID 40806523, 2025).
inflammatory breast carcinoma (1 paper, 2025). An advanced, invasive breast adenocarcinoma characterized by the presence of distinct changes in the overlying skin. "In inflammatory breast cancer, CD151, through the CD151-α6β1 integrin complex, promoted the release of MDK associated with extracellular vessels to recruit CD68+ monocytes to malignant areas." (PMID 40429950, 2025).
inflammatory liver diseases (1 paper, 2017). "Thus we propose that CD151 could be targeted to inhibit lymphocyte recruitment to the liver and prevent the progression of inflammatory liver diseases to end-stage fibrosis and reduce the risk of HCC." (PMID 28473332, 2017). "This makes CD151 a possible therapeutic target for inflammatory liver disease." (PMID 28473332, 2017).
ischemic stroke (1 paper, 2021). A stroke disorder caused by obstruction of blood flow to the brain, due to thrombotic (local blood clot formation) or embolic (due to a blood clot or other material traveling from another site) event. "However, studies have yet to clarify whether the role of tetraspanin, especially CD151, in TEMs is valuable enough to bridge the translational gap in terms of anti-adhesion molecule therapies in ischemic stroke." (PMID 34022890, 2021).
kidney cancer (1 paper, 2018). Primary or metastatic malignant neoplasm involving the kidney. "As for CD151 knockdown experiments, the upregulation of RNASEH2A was observed in all kidney cancer cell lines and was associated with impaired tumor proliferation." (PMID 29843367, 2018). "Taken together, besides RNASEH2A upregulation, the CD151-related pathway might contribute to tumor growth in CDK1-low kidney cancers." (PMID 29843367, 2018). "Upregulation of CD151 and RNASEH2A was noted 48 h after si-RNASEH2A and si-CD151 knockdown, respectively, in all kidney cancer cell lines." (PMID 29843367, 2018). "The combination of low CD151 expression and high RNASEH2A expression resulted in impaired proliferation in four kidney cancer cell lines, suggesting potential synthetic dosage lethality (SDL) interactions between the two genes." (PMID 29843367, 2018). "Our study identified that the expression of CD151 downstream genes ITGB1, ITGB4, and PLEC may have additional prognostic values in kidney cancers." (PMID 29843367, 2018).
liver fibrosis (1 paper, 2014). "This study revealed that TM4SF5 levels were positively correlated with CD151 expression but were negatively with CD63 expression during liver fibrosis and tumorigenesis." (PMID 25033048, 2014). "We found that TM4SF5 expression could override CD151 functions, and TM4SF5 acted antagonistically to CD63 during liver fibrosis development and during hepatic migration/invasive extracellular matrix (ECM) -degradation." (PMID 25033048, 2014).
malaria (1 paper, 2022). Malaria is a serious and sometimes fatal disease caused by a parasite that commonly infects a certain type of mosquito which feeds on humans. "Inhibition assays using purified anti-CD151 immunoglobulin G from rat or rabbit in RBCs infected with P. falciparum trophozoite stages (FCR3 strain) or isolates from patients with severe malaria, showed statistically significant parasite inhibition in a dose-dependent manner (~30%)." (PMID 35433504, 2022).
membranous nephropathy (1 paper, 2023). "As potential therapeutic targets, CD151 and TAPBP could be examined for creating drugs that intervene in the progression and development of membranous nephropathy." (PMID 37974210, 2023).
metastatic carcinoma (1 paper, 2011). A carcinoma which has spread from the original site of growth to another anatomic site. "It is thought that TSPAN8 contributes to the cell motility of metastatic carcinoma cell lines, mostly through its association with α6β4 and CD151 following PMA treatment, whereas association with α3β1 and α6β1 promotes haematogenic spread of tumour cells." (PMID 21081927, 2011).
Microscopic hematuria (1 paper, 2023). Microscopic hematuria detected by dipstick or microscopic examination of the urine. "A recent study described that a novel variant in CD151 was associated with nephrogenic proteinuria and microscopic hematuria, reinforcing the importance of CD151 in the pathogenesis of MN." (PMID 37974210, 2023).
myocardial ischemia (1 paper, 2013). A disorder of cardiac function caused by insufficient blood flow to the muscle tissue of the heart. "Our group focuses on the role of CD151 in angiogenesis: we previously demonstrated that delivery of the CD151 gene was capable of increasing angiogenesis in a pig myocardial ischemia model and a rat ischemic hindlimb model." (PMID 23292489, 2013).
nephritis (1 paper, 2014). Inflammation of renal tissue. "The tetraspanin CD151 binds tightly to integrin α3β1 and individuals with mutations in CD151 develop nephritis." (PMID 25352829, 2014).
renal fibrosis (1 paper, 2022). A final common manifestation of a wide variety of chronic kidney diseases characterized by glomerulosclerosis and tubulointerstitial fibrosis. "They found that miR-199a-3p is associated with TGF-β1-induced renal fibrosis by targeting CD151." (PMID 35955405, 2022).
rheumatoid arthritis (1 paper, 2020). A chronic, systemic autoimmune disorder characterized by inflammation in the synovial membranes and articular surfaces. "With naïve T cells constituting the largest T cell compartment, this means that the absolute increase in the activated CD4+CD151+ T cell population observed in HIV/ART patients, as for rheumatoid arthritis patients, is mostly driven out of the naïve T cell compartment." (PMID 32978478, 2020).
SAPHO syndrome (1 paper, 2019). SAPHO syndrome (acronym for Synovitis, Acne, Pustulosis, Hyperostosis and Osteitis) is an auto-inflammatory disease, mainly characterized by the association of neutrophilic cutaneous involvement and chronic osteomyelitis. "Other genes such as CD302, a C-type lectin receptor involved in cell adhesion and migration and CD151, known to complex with integrins and other transmembrane 4 superfamily proteins, were also up-regulated in SAPHO syndrome." (PMID 31395074, 2019).